TNFRSF10B (TNF receptor superfamily member 10b)
Diseases named in the same sentence as TNFRSF10B in open-access papers (continued):
Sharing a sentence is not in itself a finding about the gene and the disease.
Hepatitis (2 papers, 2018 to 2022). Inflammation of the liver. "Interestingly, quantities of Fasl, Fas, Tnfsf10 [TRAIL], and Tnfrsf10b [TRAIL-R2] mRNAs were over-induced especially in Ripk1LPC-KO in presence of ETA, which correlated with the worsening of hepatitis." (PMID 35806372, 2022).
kidney cancer (2 papers, 2017 to 2024). Primary or metastatic malignant neoplasm involving the kidney. "TNFRSF10B and POGLUT3 associated with kidney cancer and were also associated with other malignancies." (PMID 38684708, 2024).
mantle cell lymphoma (2 papers, 2014 to 2022). Mantle cell lymphoma is a rare form of malignant non-Hodgkin lymphoma affecting B lymphocytes in the lymph nodes in a region called the ``mantle zone''. "In a phase I trial, ONC201 triggered the ISR along with induction of CHOP and TNFRSF10B in an ibrutinib-refractory mantle cell lymphoma patient following 16 days of treatment, which aligned with therapeutic exposure to ONC201 and target engagement in the tumor." (PMID 35372029, 2022).
Parkinson's (2 papers, 2024). "The expression of TNFRSF10B in microglia of Parkinson's patients is upregulated and by inhibiting TNFRSF10B, the proinflammatory effect of microglia can be inhibited and the neural function activity can be restored." (PMID 39346794, 2024).
hypertensive renal disease (1 paper, 2026). "POLR2F, TNFRSF10B, and IGFBP2 were positively associated with all five diseases, with Mendelian randomization supporting genetic associations of POLR2F with CHD and IGFBP2 with hypertensive renal disease." (PMID 41559658, 2026).
lumbar disc degeneration (1 paper, 2024). "ANGPTL4, IGFBP3, PTGES in chondrocytes 4 and TRIB3, GDF15, TNFRSF10B in chondrocytes 5 may play an important role in the lumbar disc degeneration process." (PMID 38654287, 2024). "Some genes are widespread in chondrocyte 4, and chondrocyte 5 may play an important role in the process of lumbar disc degeneration together with the Wnt/Ca2+signaling pathway, such as ANGPTL4, PTGES, IGFBP3, GDF15, TRIB3, and TNFRSF10B." (PMID 38654287, 2024).
osteomyelitis (1 paper, 2018). An acute or chronic inflammation of the bone and its structures due to infection with pyogenic bacteria. "The TNF receptor family is involved in many of the selected inflammatory diseases, e.g., TNFRSF10B in Osteoporosis, Osteomyelitis and periodontitis, TNFRSF11B and TNFSF13B in Osteopetrosis and Periodontitis, and TNFIP6/8 in Osteomyelitis." (PMID 30497370, 2018).
postpartum hemorrhage (1 paper, 2022). Hemorrhage defined as a blood loss in excess of 500 mL after vaginal delivery or more than 1000 mL after a cesarean delivery. "Eight genes were associated with hemostatic pathways (SELL, CAPZB, SLC16A3, PDPN, TNFRSF10B, SH2B2, NFE2, and TNFRSF10D), which provided novel insights for the prevention and management of postpartum hemorrhage." (PMID 35836580, 2022).
cancer (561 papers, 2003 to 2026). A tumor composed of atypical neoplastic, often pleomorphic cells that invade other tissues. "Apoptotic-associated receptor TNFRSF10B (also known as DR5 or TRAIL-R2) has been reported to play an important role in the apoptosis of various cancer cells." (PMID 32303681, 2020). "If we infer LR interactions on the basis of correlation, then the ligand TNFSF10 secreted from the malignant cell interacts with the receptor TNFRSF10B on malignant and fibroblast cells (circled in green), indicating likely apoptosis of malignant cells and cancer-associated fibroblasts (left)." (PMID 35302849, 2022). "Moreover, signaling transduction protein PKHD1, which was mediated by receptor TNFRSF10B, could induce cancer cell proliferation and suppression of cancer cell apoptosis by the occurrence of genetic mutation and translocation." (PMID 31126066, 2019). "Overexpression of miR-519a-3p inhibits the expression of its direct target genes for TRAIL-R2 (TNFRSF10B) and caspase-8 and its indirect target gene for caspase-7; this leads to reduced apoptosis of cancer cells in response to the same apoptotic stimuli." (PMID 35741059, 2022). "TNFRSF10B/TRAIL-R2 is a TNF-related membrane receptor whose triggering by its ligand (TRAIL) transmits the apoptotic signal in cancer cells sparing normal cells." (PMID 33390181, 2021). "TNFRSF10C methylation can predict the overall survival of cancer patients 30, while the expression of TNFRSF10B can serve as a good predictor for the response of cancer cells to drug treatment." (PMID 34539886, 2021). "Increased expression of TNF‐related apoptosis‐inducing ligand (TRAIL) is observed in mesenchymal stem cell‐derived exosomes, which after interaction with death receptors 4/5 (DR4/TNFRSF10A: DR5/TNFRSF10B) mediates apoptosis specifically in cancer cells." (PMID 33751579, 2021). "A total of 8 cancer genes with an OncoScore above the 90th percentile was identified (TNFRSF10B, TNFRSF10C, TNFRSF10A, TNFRSF10D, LZTS1, NKX3-1, BNIP3L and RHOBTB2; OncoScore range: 71.4–86.3)." (PMID 28387367, 2017). "Furthermore, changes in genes involved in apoptosis signaling, such as TNFRSF10B, can lead to increased cancer cell death via alternative pathways like necroptosis." (PMID 40943317, 2025). "TNFRSF10B/DR5 delivers apoptotic signals to the cell and induces apoptosis in cancer cells." (PMID 35840882, 2022). "However, it has been shown that ER stress-induced caspase-8 activation relies on a transcriptional upregulation of Tnfrsf10b in cancer cells that express notably higher amounts of TRAIL-R2." (PMID 35075141, 2022). "Interestingly, in response to cytotoxic agents cancer cells overexpress TNFRSF10B, and this seems to be sufficient to trigger ligand-independent apoptosis." (PMID 33919224, 2021). "Therefore, as an important mediator of the extrinsic apoptotic signaling pathway, TNFRSF10B has been attracted much more attention on cancer therapy." (PMID 32303681, 2020). "TNFRSF10B has been shown to interact with FADD, caspase 10, and caspase 8 and induced apoptosis in cancer cells." (PMID 35399006, 2022). "DR4 (TNFRSF10A) and DR5 (TNFRSF10B) bind TRAIL and TNFα and can trigger cell death primarily in cancer cells." (PMID 34069424, 2021). "Many of the deregulated genes seem to be directly connected to GWAS or cancer driver genes such as TLR8, CASP1, and TNFRSF10B." (PMID 33717131, 2021). "TNFRSF10B (also known as DR5 or TRAILR2) is a protein that belongs to the TNFRSF family and mediates the extrinsic apoptotic pathway in various cancer cells." (PMID 34541005, 2021). "PKHD1, which is mediated by receptor TNFRSF10B, mutates in PTC and induces expansion of the abnormality of the centrosome leading chromosome, which then leads to genome instability that could cause malignancy, promoting cancer cell proliferation and protecting cancer cells from apoptosis." (PMID 31126066, 2019).
cancer (continued). "DR5, also known as TNFRSF10b or TRAILR2, has been discovered recently and is a well-defined tumor suppressor gene that can induce cancer cell death triggered by a variety of external stresses." (PMID 27129166, 2016). "Other proteins that are dysregulated in cancer are also affected by AIMs, including: JNK; JAK1 and STAT3; Her2 (ERBB2); death receptor 5 (TNFRSF10B); and cFLIP (CFLAR)." (PMID 25897966, 2015). "Alterations of the regulatory function of ATF3 is highlighted by our finding that ATF3 is required for both activation and repression of pro-apoptotic genes such as BBC3/PUMA and TNFRSF10B/DR5 in stress response and cancer." (PMID 22046379, 2011). "Continued research in this area may reveal their therapeutic potential, particularly KDELC2, TNFRSF10B, CPNE1, and PDIA3, paving the way for more effective cancer treatments." (PMID 37735436, 2023). "The cell surface receptor TNFRSF10B (DR5, TRAIL-R2) is commonly overexpressed on the surface of cancer cells, and in preclinical studies, its ligand TNF-related apoptosis-inducing ligand (TRAIL)-activated apoptosis selectively in cancer versus normal cells." (PMID 35086954, 2022). "In the mouse Dr5/Trail-R2/Tnfrsf10b is the only receptor of the ligand Trail (TNF-related apoptosis inducing ligand) and activation of this signaling pathway can trigger apoptosis of infectious and cancer cells." (PMID 20711434, 2010). "Finally, TNFSF10—TNFRSF10B (TRIAL—TRIAL-R), SIRPA—CD47 (“don't eat me”), C5AR1—RPS19, and GAS6—AXL act as negative regulators of the innate immune system by inhibiting cytokine responses, phagocytosis of cancer cells, and promoting the immunosuppressive TME." (PMID 37823774, 2023). "Therefore, we screened TF, proto-oncogenes, tumor suppressor genes, and other TAG from the genes adjacent to aberrant DNA methylation sites, of which multiple known cancer related genes, including MYC, DDR1, MEF2C, NDRG2, SIX1, TNFRSF10B and TSGA10, had HyperM phenomena." (PMID 26046465, 2015).
tumor (523 papers, 2003 to 2026). "The 8p21.3 risk variants rs2241261 and rs2889 (used as proxy for rs2241260, P=1.6 × 10−9, r2=0.61 with rs2241261 in CEU) are located 0.9 and 1.7 kb respectively from TNFRSF10B, a tumour suppressor gene encoding a mediator of apoptosis signalling." (PMID 28598434, 2017). "Additionally, TNFSF10 (encoding TRAIL) binds to its receptor TNFRSF10B (DR5) to induce apoptosis in tumor cells." (PMID 40891683, 2025). "The expression level of TNFRSF10B was associated with tumor progression and apoptosis." (PMID 35840882, 2022). "Consistent with our findings, several studies have demonstrated that therapies aimed at TNFRSF10B show promising anti-tumor activity in PCa and have low cytotoxicity to normal cells." (PMID 37735436, 2023). "HERV9 LTR12 induces the transcription of tumor suppressors such as germ cell-associated, transcriptionally active GTAp63 (HGNC: TP63) and TNF Receptor Superfamily Member 10b (TNFRSF10B)." (PMID 36979914, 2023). "In single cell analysis of iCCA, TRAIL-R2/TNFRSF10B was most highly expressed by endothelial cells but also expressed by tumor cells, immune cells, fibroblasts and cholangiocytes." (PMID 37404757, 2023). "From TCGA datasets, FADD, BIRC2/3, TNFSF10, and TNFRSF10B/C/D were overexpressed in tumor cases compared to normal." (PMID 33737574, 2021). "On the other hand, the expression of DR5, a member of the tumor necrosis factor receptor superfamily (TNFRSF10B), was previously correlated with radiosensitivity in tumor cells." (PMID 34372869, 2021). "To study if TRAILR2 is required for TRAIL hypersensitization within tumor cell spheroids, we targeted TNFRSF10B by CRISPR/Cas9-mediated gene knockout." (PMID 32433558, 2020). "As an example of an Under-UpT gene with potential tumor-suppressor activity we report the TNFRSF10B gene (also known as DR5)." (PMID 30287863, 2018). "TNFRSF10B inhibits tumor formation through apoptosis but deregulation encourages metastasis, migration and invasion of tumor cell tissues." (PMID 23724937, 2013). "Furthermore, in this study, we demonstrated that SLC25A5, PPIA, and TNFRSF10B were correlated with tumor immune microenvironment infiltration and may be potential prognostic biomarkers for ESCA." (PMID 35840882, 2022). "The 8 SNPs (CD3EAP rs967591, TNFRSF10B rs1047266, AKT1 rs3803300, C3 rs2287845, HOMER2 rs1256428, GNB2L1 rs3756585, ADAMTSL3 rs11259927, and CD3D rs3181259) were found to be significantly associated with OS and/or DFS when adjusted for age, gender, smoking status, tumor histology, pathologic stage." (PMID 26462029, 2015). "The secreted protein genes WNT5A, VEGFA, and SEMA3A, and the receptor genes AXL, TNFRSF10B and IGF1R were mainly expressed by tumor cells." (PMID 37823774, 2023). "Since our results showed an upregulation of TNFRSF10B after irradiation in GOT1 tumors at both time points, regardless of A1M administration, it seems likely that A1M can affect normal and tumor tissues differently." (PMID 37076494, 2023). "MiR-519a-3p diminished the expression of its direct target genes for TRAIL-R2 (TNFRSF10B) and for caspase-8 (CASP8) and its indirect target gene for caspase-7 (CASP7), resulting in reduced sensitivity and tumor cell apoptosis in response to apoptotic stimuli." (PMID 28771222, 2017). "All GOT1 tumor sections, irrespective of treatment, contained weak cytoplasmic staining of TNFRSF10B." (PMID 37076494, 2023).
tumor (continued). "Due to the tumor-specific cytotoxicity of TRAIL, its recombinant version and agonistic antibodies against the death-inducing TRAIL receptors (TNFRSF10A/DR4, TNFRSF10B/DR5) are currently being tested in Phase I/II clinical trials." (PMID 25527049, 2014).
infection (32 papers, 2006 to 2025). The state of being infected such as from the introduction of a foreign agent such as serum, vaccine, antigenic substance or organism. "Interestingly, the levels of the CHOP (DDIT3), DR5 (TNFRSF10B), ATF3, and SESN2 proteins were dramatically increased in CYB5R3-overexpressing H1299 and H1703 cells following Ad-CYB5R3 infection." (PMID 38253797, 2024).
adenocarcinoma (5 papers, 2010 to 2023). A common cancer characterized by the presence of malignant glandular cells. "The cell surface receptor TNFRSF10B (or death receptor 5-DR5), from the tumor necrosis factor family, mediates the extrinsic apoptosis pathway, and its upregulation is associated with BE-related adenocarcinomas." (PMID 35328735, 2022).
neurodegenerative disease (1 paper, 2024). A disorder of the central nervous system characterized by gradual and progressive loss of neural tissue and neurologic function. "Our comparative analysis of RHBDF2 and TNFRSF10B expression in various neurodegenerative diseases has revealed that their heightened expression is distinctive to AD, contrasting conditions like PD, FTD, DLB, and HD." (PMID 38915415, 2024). "Expression characteristics of RHBDF2 and TNFRSF10B in multiple neurodegenerative diseases." (PMID 38915415, 2024).
TNFRSF10B also shares sentences with these, for which no sentence is quoted: glioblastoma (39 papers); glioma (38); renal carcinoma (27); cervical cancer (15); myeloma (15); lymphoma (14); head and neck cancer (9); oral cancer (9); osteosarcoma (9); viral infection (9); liver cancer (8); pancreatic ductal adenocarcinoma (8); multiple myeloma (7); triple-negative breast carcinoma (7); colorectal tumor (6); esophageal cancer (6); rheumatoid arthritis (6); acute lymphoblastic leukaemia (5); acute myocardial infarction (5); brain tumor (5); chondrosarcoma (5); chronic lymphocytic leukemia (5); head and neck squamous cell carcinoma (5); influenza infection (5); liver fibrosis (5); Arthritis (4); Burkitt lymphoma (4); diabetes (4); lymph node metastasis (4); myeloid leukemia (4).
A further 161 diseases each share a sentence with TNFRSF10B in 4 papers or fewer.